MIR21 (microRNA 21)
Synonyms: hsa-mir-21; MIR-21; MIRN21; miRNA21
Gene: MicroRNA gene on chromosome 17 (59,841,266 to 59,841,337, forward strand). Ensembl gene ENSG00000284190.
Pathways (Reactome):
Disease: Nuclear events stimulated by ALK signaling in cancer
Gene Ontology:
Cellular component: RISC complex
Homologues: Orthologues: chimpanzee ptr-mir-21 (100% identical), macaque mml-mir-21 (100% identical), dog MIR21 (99% identical), guinea pig MIR21 (99% identical), pig ssc-mir-21 (99% identical), mouse Mir21a (97% identical), rabbit MIR21 (83% identical), zebrafish dre-mir-21-2 (79% identical).
Diseases named in the same sentence as MIR21 in open-access papers:
MIR21 is named in the same sentence as 37 diseases in open-access papers, as found by Europe PMC text mining. Sharing a sentence is not in itself a finding about the gene and the disease. The quoted sentences say what the papers report.
breast cancer (9 papers, 2012 to 2023). A primary or metastatic malignant neoplasm involving the breast. "High circulatory MIR21 levels have also been linked to poor prognoses in patients with B lymphoma and mammary tumors." (PMID 35765483, 2022). "The top candidate, MIR21, was suggested as a potential diagnostic marker of colorectal cancer and involved in tumor growth in breast cancer." (PMID 24308539, 2013). "MIR21 was found to be the most abundant in mammary tumor cell culture, while MIR10B and MIR30E were found to be the most abundant in lymphoid tumor cell culture (Figure-3)." (PMID 35765483, 2022). "Chemotherapy alters the DNA methylation pattern in leukocytes of breast cancer patients and the CpG cg16936953 in the VMP1/MIR21 gene is associated with cognitive decline in breast cancer patients." (PMID 32457596, 2020). "Similarly, several exosome-derived miRNA orthologs previously reported for increased expression in both canine and human mammary tumor cell lines, including MIR21, MIR106B, MIR181A1, MIR183, MIR200B, and MIRLET7G, were presented." (PMID 35765483, 2022). "However, the changes of VMP1/MIR21 mRNA after paclitaxel treatment were inversely correlated with the respective paclitaxel IC50 concentrations in the detected breast cancer cells." (PMID 29392887, 2018). "On the other hand, further studies are still needed to explore the role of VMP1/MIR21 in the mechanism for the paclitaxel resistance of TNBCs as miR‐21 has been shown to be a useful biomarker to predict neoadjuvant therapeutic response in breast cancer patients." (PMID 29392887, 2018).
breast tumor (2 papers, 2021 to 2024). "High expression from genes neighboring MIR21 has been reported in breast tumors." (PMID 34797887, 2021). "Summary figures for SE regions near VMP1/MIR21 (Chr 17), SUMO1P1 (Chr 20), and PVT1 (Chr 8) are shown as representative examples from cluster A, B, and D, respectively, showing higher accessibility in non-basal compared with basal breast tumor samples." (PMID 38625038, 2024).
diabetic kidney disease (2 papers, 2022). Progressive kidney disorder caused by vascular damage to the glomerular capillaries, in patients with diabetes mellitus. "Increased urinary Mir-21 expression was also confirmed in patients with diabetic kidney disease (DKD), IgA nephropathy and polycystic kidney disease (PKD)." (PMID 34312814, 2022). "The MIR21 gene, located in TMEM49 gene on chromosome 17q23.2, has been well characterized in many complications diabetes-related, such as diabetic retinopathy, kidney fibrosis, diabetic nephropathy, and insulin resistance (IR)." (PMID 35246121, 2022).
Obesity (2 papers, 2012 to 2019). Accumulation of substantial excess body fat. "Mir-21, here significantly associated with obesity phenotypes, has been reported to be involved in regulation of adipogenesis and lipid metabolism through its gene targets TGFBR2 and PPARalpha respectively." (PMID 22589741, 2012). "Moreover, CpGs in the VMP1/MIR21 locus are also among the top hits in several previous EWAS, including chronic inflammation marker C-reactive protein (CRP), cardiovascular biomarker GDF-15, obesity, childhood-onset Crohn’s disease, and inflammatory bowel disease." (PMID 30867049, 2019).
clear cell renal cell carcinoma (1 paper, 2020). "We also confirmed MIR21 hypomethylation by pyrosequencing of fresh clear cell renal cell carcinoma (ccRCC) samples." (PMID 32637580, 2020).
Duchenne muscular dystrophy (1 paper, 2017). Duchenne muscular dystrophy (DMD) is a neuromuscular disease characterized by rapidly progressive muscle weakness and wasting due to degeneration of skeletal, smooth and cardiac muscle. "Mir-21 has been shown to be involved in the fibrogenic pathway and the progression of Duchenne muscular dystrophy, so may play a role in muscle remodelling during exercise training." (PMID 29166903, 2017).
heart failure (1 paper, 2011). Inability of the heart to pump blood at an adequate rate to meet tissue metabolic requirements. "Mir-21 is known to be up-regulated in many forms of cancer as well as in the heart during cardiac hypertrophic growth and heart failure." (PMID 21303526, 2011).
lung carcinoma (1 paper, 2022). "Using a bioinformatic tool, Lung Cancer Explorer, we performed a correlation analysis between expression for precursor MIR21 and ADSL mRNA across 292 lung cancer patient tissues." (PMID 35840668, 2022).
melanoma (1 paper, 2016). A malignant, usually aggressive tumor composed of atypical, neoplastic melanocytes. "The expression of MIR21 has further been shown to increase during melanoma progression and to predict poor survival." (PMID 26918341, 2016). "Another potential therapy target is MIR21, which we found to be highly upregulated in primary melanomas (significant upregulation validated using qRT-PCR, data not shown)." (PMID 26918341, 2016). "Consistent with this, we found that both CXCR4 and MIR21 were upregulated in metastatic compared to non-metastatic primary melanomas." (PMID 26918341, 2016).
osteoporosis (1 paper, 2024). A condition of reduced bone mass, with decreased cortical thickness and a decrease in the number and size of the trabeculae of cancellous bone (but normal chemical composition), resulting in increased fracture incidence. "Mir-21 ablation also attenuated OVX-induced osteoporosis and aging-induced osteoporosis, which was validated in osteoporosis patients." (PMID 38644509, 2024).
osteosarcoma (1 paper, 2017). A usually aggressive malignant bone-forming mesenchymal neoplasm, predominantly affecting adolescents and young adults. "A minus 3-fold (=minus 70%) ibandronate-induced downregulation of MIR21 in the U-2 OS osteosarcoma cells might be associated with the known drug-induced RAS-inactivation in this cell line." (PMID 28914765, 2017).
ovarian carcinoma (1 paper, 2023). A malignant neoplasm originating from the surface ovarian epithelium. "Moreover, we identified differences in the methylation status of the MIR21 gene, which is linked to chemotherapy resistance in various cancers, such as ovarian cancer and renal carcinoma." (PMID 38069103, 2023).
prostate carcinoma (1 paper, 2018). A carcinoma that arises from epithelial cells of the prostate gland. "In prostate cancer cell lines, MIR21 promoter hypermethylation resulted in its repressed expression." (PMID 30454026, 2018).
squamous cell carcinoma (1 paper, 2020). A carcinoma arising from squamous epithelial cells. "Previously, the deletion of the MIR21 gene locus by TALEN and CRISPR/Cas9 technologies revealed a substantially impaired oncogenic potential of HeLa cells and independent, oncogenic roles of miR-21-5p/3p in squamous cell carcinoma stem cells." (PMID 34316687, 2020).
thyroid cancer (1 paper, 2018). "MIR21 overexpression was previously reported in thyroid cancer." (PMID 30454026, 2018).
ulcerative colitis (1 paper, 2012). An inflammatory bowel disease involving the mucosal surface of the large intestine and rectum. "Mir-21 has previously been shown to be increased in active ulcerative colitis and upregulated during DNA damage by hydrogen peroxide and ionizing radiation associated with reactive oxygen species." (PMID 22970173, 2012).
cancer (17 papers, 2011 to 2025). A tumor composed of atypical neoplastic, often pleomorphic cells that invade other tissues. "The oncogenic role of Mir21 is strongly linked to advanced cancer phenotypes, including enhanced cell survival and inflammation." (PMID 40869212, 2025). "Mir-21 expression is associated with cancer stem cell properties and is involved in stemness maintenance in multiple cancers, including pancreatic ductal adenocarcinoma cells." (PMID 35740906, 2022). "MIR21 is well studied in cancer and is reported as a potential diagnostic, prognostic, and predictive biomarker in many cancer types, including breast cancer." (PMID 34797887, 2021). "GSEA of genes ranked by their fold change of expression upon MIR21 deletion indicated a striking downregulation of proliferation-associated gene sets, e.g. E2F_target and G2M_checkpoint, as well as other cancer-associated hallmark gene sets like MTORC1_signaling." (PMID 34316687, 2020). "We identify MIR21 upregulation as the cause of JAM-A downregulation and show that JAM-A rescue mitigates the effects of MIR21 overexpression on cancer phenotype." (PMID 34226680, 2021). "Taken together, we identified a SE associated with the MIR21 gene driven by FOSL1 in HNSCC, which uncovers a novel mechanism underlying miR-21-5p regulation in cancer." (PMID 33937067, 2021). "Deletion of the MIR21 locus in cancer-derived cells identifies several direct and indirect miR-21-5p targets, including major tumor suppressors with prognostic value across cancers." (PMID 34316687, 2020). "According to these well-established functions of EI24, GNGT2 and MIR21, PanDM’s identification of their DM status in cancers is highly likely to reflect a biological reality." (PMID 33087120, 2020). "Mir-21 has been very well studied and has been shown to be crucial in many biological pathways and diseases, including cardiovascular disease and several cancers." (PMID 29871895, 2018). "To demonstrate the expression of MIR21 in tumors and its relationship with tumor prognosis, we downloaded the expression analysis data of hsa-miR-21-5p in 17 cancer types from the starBase website and the correlation data for hsa-miR-21-5p expression and survival time of patients with tumor." (PMID 32637580, 2020). "MIR21 is an anti-apoptotic factor that is ubiquitously found in cancer cells." (PMID 32393269, 2020). "In addition, there is evidence that levels of circulating MIR21 can define the prognosis of cancer patients and may act as surrogate for miRNA expression in the tumour." (PMID 29113809, 2018). "Given that 3D assays appear to recapitulate more closely the in vivo cancer physiology, we further validated our findings in a 3D migration assay using the DLD-1 cell line and confirmed that MIR21 overexpression induced increased migration also in 3D spheroid conditions." (PMID 34226680, 2021). "Mir-21 high expression was demonstrated to moderately predict poor OS regardless of the site of cancer (HR = 1.903, 95% CI: 1.713–2.113, P = 0.000)." (PMID 25098165, 2014).
tumor (11 papers, 2013 to 2022). "Besides targets regulating apoptosis, MIR21 also has the potential to regulate pathways associated with cell cycle arrest, suppression of tumor growth, and chromosome assembly." (PMID 32393269, 2020). "The deletion of MIR21 significantly impaired tumor growth and resulted in substantially diminished final tumor volume and mass." (PMID 34316687, 2020). "MIR21 expression was confirmed to be inactivated in the tumor after withdrawal of doxycycline diet, while an increase in DNAJB5 protein expression was detected." (PMID 29113809, 2018). "This identified various validated tumor suppressors upregulated upon MIR21 deletion." (PMID 34316687, 2020). "We observed that MIR21 can drive tumor cell proliferation in the presence of HSP90 inhibitors." (PMID 29113809, 2018). "In conclusion, MIR21 could be a sensitive biomarker reflecting tumor status." (PMID 32759718, 2020). "Only MIR10B, MIR21, and MIR30E inherited RP scores of <10 and were thus chosen as candidate orthologs for further tumor classification analysis using the SVM model." (PMID 35765483, 2022). "Mir-21 has been inversely related to apoptotic processes, so we studied the expression of the PARP-1 protein, and this was directly related to tumor vascular increase, so we also studied the VEGF protein." (PMID 36499129, 2022).
infection (2 papers, 2015 to 2018). The state of being infected such as from the introduction of a foreign agent such as serum, vaccine, antigenic substance or organism. "Enforced expression of MIR21 significantly increased resistance to AUY922 (P < .05), when compared with the effect of infection with an empty CTRL vector." (PMID 29113809, 2018).
MIR21 also shares sentences with these, for which no sentence is quoted: cognitive decline (2 papers); colorectal cancer (2); cardiovascular disease (1); cholangiocarcinoma (1); colon cancer (1); Crohn disease (1); diabetes (1); diabetic retinopathy (1); Epstein-Barr virus infection (1); hematological malignancies (1); IgA nephropathy (1); inflammatory bowel disease (1); Insulin resistance (1); lung squamous cell carcinoma (1); lymphoid tumor (1); myeloma (1); polycystic kidney disease (1); renal carcinoma (1).